PELI1 (pellino E3 ubiquitin protein ligase 1)
Diseases named in the same sentence as PELI1 in open-access papers (continued):
Sharing a sentence is not in itself a finding about the gene and the disease.
psoriasis (continued). "In the present study, we found that inducible overexpression of Peli1 for less than 6 months triggered severe psoriasis and a few comorbidities but not B cell lymphoma." (PMID 32873845, 2020). "Further histopathological analysis showed that Pepboy. chimeric mice receiving rtTA-Peli1 BM cells (group 4) showed no significant signs of psoriasis-like phenotype, implying that overexpression of Peli1 in lymphocytes only was insufficient to develop psoriatic lesions." (PMID 32873845, 2020).
B cell lymphoma (3 papers, 2017 to 2023). "Our recent study strongly indicates that Peli1 expression is upregulated in patients with B cell lymphoma and that such upregulation is associated with poor prognosis." (PMID 32873845, 2020). "In addition, Peli1 is overexpressed in the majority of patients with aggressive B cell lymphoma, and Peli1 expression appears to be closely associated with poor prognosis among B cell lymphoma patients." (PMID 28410192, 2017). "In mice, overexpression of Peli1 stabilizes Bcl6 resulting in B cell lymphomagenesis, and in diffuse large B cell lymphoma (DLBCL) patients, poor prognosis is followed by a higher level of Peli1 and Bcl6, indicating that Peli1 is a novel oncogenic signal in B cell lymphoma." (PMID 37176148, 2023). "In support of this hypothesis, we also identified that the levels of Peli1 protein were highly elevated, particularly in a number of cells from cancer patients, such as aggressive B cell lymphomas." (PMID 28410192, 2017). "However, we cannot exclude the possibility that inducible Tg mice might develop B cell lymphoma at a later period, as shown in conventional Peli1 Tg mice overexpressing constitutively low levels of Peli113." (PMID 32873845, 2020).
diffuse large B-cell lymphoma (3 papers, 2022 to 2025). "The highest frequency of PELI1 alterations was observed in patients with diffuse large B-cell lymphoma, primarily in the form of copy number amplification, while R145Q/W represented the most recurrent mutation sites." (PMID 41562077, 2025). "Diffuse large B-cell lymphoma (DLBC) exhibited the highest PELI1 alteration frequency, predominantly involving copy number amplification (CNA)." (PMID 41562077, 2025). "Previous studies have reported that PELI1 can serve as a prognostic biomarker in cancers such as diffuse large B-cell lymphoma and pancreatic cancer." (PMID 41562077, 2025). "Background/Aim: Peli1 is an E3 ubiquitin ligase involving lymphomagenesis by lysine 63 ubiquitination-mediated stabilization of Bcl-6 with in diffuse large B-cell lymphoma (DLBCL)." (PMID 36606193, 2022).
melanoma (3 papers, 2022 to 2023). A malignant, usually aggressive tumor composed of atypical, neoplastic melanocytes. "The diverse roles of Peli1 in the different phases of melanoma progression warrant further investigation." (PMID 38179042, 2023). "However, Peli1 plays contradictory roles in melanoma progression." (PMID 38179042, 2023). "In addition, PELI1 could regulate the metabolic actions of mTORC1 to suppress antitumor T cell responses in melanoma." (PMID 34991623, 2022). "In contrast Peli1 is involved in palmitate-induced, TLR4-dependent lung metastasis in melanoma." (PMID 38179042, 2023). "Given the role of Peli1 in other tumors and that of TLR4/NF-κB in melanomas, this study examined the effect of Peli1 and the related signaling pathways that influence the occurrence and development of melanomas." (PMID 36422271, 2022). "However, the function and related signal transduction of Peli1 in melanomas are not clear." (PMID 36422271, 2022).
multiple sclerosis (3 papers, 2016 to 2021). A progressive autoimmune disorder affecting the central nervous system resulting in demyelination. "Considering the essential pathogenic role of Peli1 in driving microglia-mediated neurodegeneration like multiple sclerosis and AD, we proposed that microglial Peli1 may be a critical novel therapeutic target that have clinical potential for the neurodegenerative diseases." (PMID 33017390, 2020). "The ubiquitin ligase Peli1 has previously been suggested as a potential treatment target in multiple sclerosis." (PMID 27746629, 2016). "We had previously reported that Peli1 could regulate microglia-mediated CNS inflammation in a multiple sclerosis mouse model." (PMID 33017390, 2020). "Further studies of Peli1 interaction partners and cell-type specific signaling pathways are needed to specifically modulate the effects observed by Peli1 KO to introduce new therapies to treat neurodegenerative diseases like multiple sclerosis." (PMID 27746629, 2016).
squamous cell carcinoma (3 papers, 2017 to 2025). A carcinoma arising from squamous epithelial cells. "Immunofluorescence assays detected high PELI1 expression in various cancer cell lines, including Caco-2 epidermoid carcinoma, Hela cervical adenocarcinoma, and U2OS osteosarcoma cells." (PMID 41562077, 2025). "To confirm the pro‐apoptotic function of PELI1, we examined the role of PELI1 in regulating IR‐induced apoptosis in other two types of human squamous cell carcinoma cell lines SCC‐9 and SiHa." (PMID 34738714, 2022). "Correspondingly, PELI1 knockdown specifically promoted the expression of the Bcl‐XL protein in IR‐treated TE‐1, ECA‐109, SCC‐9 and SiHa squamous carcinoma cells, while overexpression of PELI1 also reduced the Bcl‐XL protein levels in these tumor cells." (PMID 34738714, 2022). "However, our present study showed that the expression of PELI1 in ESCC was significantly lower than that of matched normal tissues, and PELI1 functioned as a tumor suppressor to regulate the radiosensitivity in squamous carcinomas cells." (PMID 34738714, 2022). "As expected, PELI1 knockdown significantly promoted the accumulation of NIK proteins and thus enhanced the activation of the IR‐induced noncanonical NF‐κB signaling pathway in TE‐1, ECA‐109, SCC‐9 and SiHa squamous carcinoma cells, resulting in enhanced p52 and RelB entry into the nucleus." (PMID 34738714, 2022). "The results revealed that IR did not affect the PELI1 expression at both mRNA and protein levels in TE‐1, ECA‐109 and other two types of human squamous cell carcinoma cell lines SCC‐9 (tongue squamous cell line) and SiHa (cervical squamous cancer cell line)." (PMID 34738714, 2022).
ZIKV infection (3 papers, 2020 to 2024). "Here, in our murine model, ZIKV infection caused an acute increase of placental Peli1 expression, which was accompanied by placental inflammation, tissue damage, and severe congenital malformations." (PMID 32544190, 2020). "Overall, our findings suggest Peli1 contributes to CZS by facilitating ZIKV infection, and promoting ZIKV vertical transmission and neuronal loss." (PMID 32544190, 2020). "Peli1 promotes Zika virus (ZIKV) infection and placental inflammation and is involved in multiple stages of ZIKV infection, including cellular attachment, entry, replication, and translation." (PMID 38179042, 2023). "During ZIKV infection, Peli1 promotes ZIKV infection and placental inflammation, exacerbating congenital abnormalities." (PMID 38179042, 2023). "We also noted that fetal tissues collected from Peli1-/- dams on E13.5 showed lower viral loads following a high dose of ZIKV infection at E6.5." (PMID 32544190, 2020). "Peli1 expression was upregulated following ZIKV infection in hNS/PCs derived from human fetal brain tissues." (PMID 32544190, 2020). "Using the same method, we measured Peli1 overexpression during ZIKV infection of 293T cells overexpressing Peli1 or empty vector." (PMID 32544190, 2020). "On day 4, ZIKV infection was decreased in HTR8 cells infected with virus passaged in Peli1 siRNA treated cells." (PMID 32544190, 2020). "To increase ZIKV permissiveness, we blocked type I IFNR signaling by anti-ifnar antibody in WT and Peli1−/− macrophages followed by ZIKV infection." (PMID 32544190, 2020). "In summary, these results indicate that Peli1 expression is induced following ZIKV infection and it is involved in the cell attachment, entry, and translation stages of ZIKV life cycle." (PMID 32544190, 2020). "The levels of cytokines, including Il1b, Tnfa, and Il12, were all diminished in Peli1−/− macrophages following ZIKV infection." (PMID 32544190, 2020). "Our data showed that Peli1 expression was enhanced on human PBMCs and human monocyte cells following ZIKV infection." (PMID 32544190, 2020). "Here, we found that Peli1 expression was enhanced in human monocytic cells, peripheral blood mononuclear cells, first-trimester placental trophoblasts and neural stem cell (hNSC)s following ZIKV infection." (PMID 32544190, 2020). "Immunofluorescence staining was next performed following ZIKV infection (MOI 10) of HTR8 cells in order to determine whether Peli1 is involved in the ZIKV life cycle." (PMID 32544190, 2020). "Peli1 knockdown in HTR8 cells led to reduced cell death rates following ZIKV infection." (PMID 32544190, 2020). "Thus, Smaducin-6 may inhibit ZIKV infection and induction of innate cytokine responses via interacting with Peli1." (PMID 32544190, 2020). "Thus, Peli1 may directly induce cell death or indirectly by mediating the inflammatory cytokine responses in trophoblasts and hNSCs upon ZIKV infection." (PMID 32544190, 2020). "Peli1 is also upregulated on ZIKV-infected first trimester placental trophoblasts and hNS/PCs, which together indicates a role of Peli1 in ZIKV infection in humans." (PMID 32544190, 2020). "Collectively, these results suggest that Peli1 expression is upregulated in ZIKV- infected human PBMCs and monocytic cells, and it promotes ZIKV infection and induction of inflammation and cell death in human placental trophoblasts." (PMID 32544190, 2020). "Here, we noted that Peli1 expression was 40 to 58% higher on human monocytic cells (THP-1 cells) and peripheral blood mononuclear cells (PBMCs) following ZIKV infection." (PMID 32544190, 2020). "Smaducin-6, a membrane-tethered Smad6-derived peptide, blocked Peli1-mediated NF-κB activation but did not have direct effects on ZIKV infection." (PMID 32544190, 2020).
acute kidney injury (2 papers, 2022 to 2023). Sudden and sustained deterioration of the kidney function characterized by decreased glomerular filtration rate, increased serum creatinine or oliguria. "In septic acute kidney injury (AKI), DAPK1 Peli1 phosphorylation promotes RIP1 binding to caspase-8 and ultimately induces tubular apoptosis." (PMID 38179042, 2023).
Alzheimer disease (2 papers, 2020 to 2022). A progressive, neurodegenerative disease characterized by loss of function and death of nerve cells in several areas of the brain leading to loss of cognitive function such as memory and language. "Correspondingly, deletion of Peli1 enhances Aβ phagocytosis and clearance in Alzheimer’s disease, implicating Peli1 as a therapeutic target with significant potential for the treatment of microglia-mediated neurological disease." (PMID 33017390, 2020).
asthma (2 papers, 2020 to 2023). "Elevaed Peli1 expression is associated with severity and relapse of asthma in patients." (PMID 38179042, 2023). "Peli1 regulates the pro-inflammatory response of airway epithelial cells in patients with asthma, and Peli1 knockdown significantly reduces CXCL8 expression in the airway epithelium of these patients." (PMID 38179042, 2023). "E levation of IL-1 signaling factors, including Peli1, contributes to in childhood asthma." (PMID 38179042, 2023). "In addition, Peli1 is upregulated in neutrophilic asthma patients." (PMID 32873845, 2020). "In summary, Peli1 predominantly plays a pro-inflammatory role in COPD, asthma, acute lung injury, and PBB." (PMID 38179042, 2023).
cardiac hypertrophy (2 papers, 2024 to 2025). "In conclusion, the present study provides compelling evidence that the regulatory effect of Peli1 on HNF4α plays a crucial role in the impairment of FAO during pathological myocardial hypertrophy caused by pressure overload." (PMID 38346961, 2024). "To investigate the potential role of Peli1 during cardiac hypertrophy in vivo, we conducted TAC surgery on WT mice and Peli1KO mice for 4 weeks." (PMID 38346961, 2024). "Peli1 systemic knockout mice (Peli1KO) display improved myocardial hypertrophy and cardiac function following transverse aortic constriction (TAC)." (PMID 38346961, 2024). "Consistent with previous studies, Peli1 knockout significantly improved TAC-induced cardiac hypertrophy, but this was significantly suppressed by BI6015 administration." (PMID 38346961, 2024). "Consistent with previous studies, our research observed the significant impact of Peli1 on the transcriptome of signaling processes in cardiac hypertrophy." (PMID 38346961, 2024). "Thus, Peli1 plays a crucial role in TAC-induced pathological myocardial hypertrophy by promoting the ubiquitinated degradation of HNF4α and affecting FAO (Graphical Abstract)." (PMID 38346961, 2024). "To validate whether the beneficial effect of Peli1 knockout on cardiac hypertrophy relies on HNF4α, we utilized the HNF4α antagonist BI6015." (PMID 38346961, 2024). "In this study, we aimed to investigate the involvement of HNF4α and its ubiquitination, facilitated by Peli1, in FAO during pressure overload-induced cardiac hypertrophy." (PMID 38346961, 2024). "We further used the antagonist BI6015 to inhibit HNF4α and delivered rAAV9-HNF4α to elevate myocardial HNF4α level, and confirmed that HNF4α inhibits the development of cardiac hypertrophy after TAC and is essential for the enhancement of FAO mediated by Peli1 knockout." (PMID 38346961, 2024). "Notably, TAC-induced cardiac hypertrophy observed in WT mice was significantly inhibited by the absence of Peli1." (PMID 38346961, 2024). "In this study, we provide evidence that the absence of Peli1 confers protection against pathological cardiac hypertrophy by suppressing the ubiquitination of HNF4α and enhancing the expression of FAO-related genes in the myocardium under pressure overload conditions." (PMID 38346961, 2024).
colon adenocarcinoma (2 papers, 2025). "Hypermethylation of PELI1 occurred in colon adenocarcinoma (COAD), HNSC, KIRC, LUAD, READ, SKCM, thyroid carcinoma (THCA) and UCEC, while hypomethylation was observed in kidney renal papillary cell carcinoma (KIRP), LIHC, prostate adenocarcinoma (PRAD)." (PMID 41562077, 2025).
congenital Zika syndrome (2 papers, 2021 to 2023). "Another study also demonstrated that Smadcin‐6, a Smad6‐derived peptide, interacts with Peli1 to disrupt Peli1‐mediated TLR4 signalling, and that it also showed therapeutic effects in lethal inflammatory disease and congenital Zika syndrome." (PMID 37341064, 2023).
COVID-19 (2 papers, 2021 to 2023). A disease caused by infection with severe acute respiratory syndrome coronavirus 2. "Several of these genes (PELI1, MAP3K8, LAMA3, EMP2, CTNNAL1, CAV1, LRRK2, SFRP4) may also be involved in lung fibrosis, a severe complication of COVID-19." (PMID 37561814, 2023).
Flavivirus Infections (2 papers, 2020 to 2024). Infections with viruses of the genus FLAVIVIRUS, family FLAVIVIRIDAE. "Thus, Peli1-mediated differential innate immune signaling contributes to various disease outcomes during flavivirus infection." (PMID 32544190, 2020).
idiopathic pulmonary fibrosis (2 papers, 2022 to 2023). Idiopathic pulmonary fibrosis (IPF) is a nonneoplastic pulmonary disease that is characterized by the formation of scar tissue within the lungs in the absence of any known cause. "Double-stranded RNA adenosine deaminase 1 (ADAR1) is significantly down-regulated in fibroblasts derived from Idiopathic Pulmonary Fibrosis (IPF) patients, and its overexpression restored levels of miRNA-21, PELI1, and SPRY2." (PMID 36012303, 2022).
myocarditis (2 papers, 2021 to 2023). Myocarditis is a condition that is characterized by inflammation of the heart muscle (myocardium). "In an LPS-induced myocarditis model, Peli1 activatio was associated with promoting pro-inflammatory genes, and si-Peli1 treatment alleviated or reversed LPS-induced cellular injury by altering cardiomyocyte energy metabolism." (PMID 38179042, 2023). "In an LPS-induced myocarditis model, Peli1 was activated and promoted pro-inflammatory genes expression." (PMID 38179042, 2023).
osteosarcoma (2 papers, 2022 to 2025). A usually aggressive malignant bone-forming mesenchymal neoplasm, predominantly affecting adolescents and young adults. "In addition, PELI1 has been reported to inhibit the radiosensitivity in osteosarcoma U2OS cells." (PMID 34738714, 2022).
papillary thyroid carcinoma (2 papers, 2022 to 2023). "MiRNAs have been explored as regulators of Peli1 and human umbilical cord mesenchymal stem cell-derived extracellular vesicles modified with miR-30c-5p effectively suppress Peli1 expression and inhibit papillary thyroid carcinoma progression in vitro and in vivo." (PMID 38179042, 2023).
Stroke (2 papers, 2023 to 2025). Sudden impairment of blood flow to a part of the brain due to occlusion or rupture of an artery to the brain. "Elevated Peli1 levels are associated with a high risk of stroke in patients with atrial fibrillation, suggesting its potential use as a marker for stroke prediction, prevention, and treatment in this population." (PMID 38179042, 2023). "Previous studies have suggested PELI1 as a biomarker to improve the prediction, prevention, and treatment of stroke in atrial fibrillation patients, consistent with our results." (PMID 40124544, 2025).
ulcerative colitis (2 papers, 2023 to 2025). An inflammatory bowel disease involving the mucosal surface of the large intestine and rectum. "BBT-401, a pharmacologically targeted Peli1 inhibitor developed by Bridge Biotherapeutics, is undergoing phase II clinical trials to treat ulcerative colitis." (PMID 38179042, 2023).
acute myeloid leukemia (1 paper, 2025). Acute myeloid leukemia (AML) is a group of neoplasms arising from precursor cells committed to the myeloid cell-line differentiation. "Our findings revealed that elevated PELI1 expression was consistently associated with worse overall survival (OS) in several tumor types, including leukemia, acute myeloid leukemia (LAML), LIHC, mesothelioma (MESO) and sarcoma (SARC)." (PMID 41562077, 2025).
atopic dermatitis (1 paper, 2020). "Next, we tested Peli1 expression in lesional specimens obtained from 2,4-dinitrochlorobenzene (DNCB)-induced atopic dermatitis, a model of inflammation." (PMID 32873845, 2020).
bladder urothelial carcinoma (1 paper, 2025). "Lung squamous cell carcinoma (LUSC) and bladder urothelial carcinoma (BLCA) also showed substantial PELI1 amplification." (PMID 41562077, 2025).
breast invasive carcinoma (1 paper, 2025). "Pathological stage progression correlated with increasing PELI1 expression in LIHC, KIRC, CHOL, ESCA, and STAD, but decreasing levels in breast invasive carcinoma (BRCA), kidney chromophobe (KICH), rectal adenocarcinoma (READ), and UCEC." (PMID 41562077, 2025).
cardioembolic stroke (1 paper, 2024). "The study analyzing high-throughput gene expression in blood samples has shown that the circulating gene expression makers including CREM, PELI1, and ZAK were verified to be up-regulated in cardioembolic stroke." (PMID 38166912, 2024).
clear cell renal cell carcinoma (1 paper, 2026). "In individuals with clear cell renal cell carcinoma (ccRCC), Peli1 exhibits markedly elevated expression, and this upregulation is associated with adverse clinical outcomes." (PMID 41786698, 2026).
colorectal cancer (1 paper, 2025). A primary or metastatic malignant neoplasm that affects the colon or rectum. "Additionally, elevated PELI1 levels were observed in clinical specimens from liver, breast, prostate, lung, and colorectal cancers." (PMID 41562077, 2025).